UCHL3 (ubiquitin C-terminal hydrolase L3)
Description:
Deubiquitinating enzyme (DUB) that controls levels of cellular ubiquitin through processing of ubiquitin precursors and ubiquitinated proteins. Thiol protease that recognizes and hydrolyzes a peptide bond at the C-terminal glycine of either ubiquitin or NEDD8. Has a 10-fold preference for Arg and Lys at position P3'', and exhibits a preference towards 'Lys-48'-linked ubiquitin chains. Can hydrolyze UBB(+1), a mutated form of ubiquitin which is not effectively degraded by the proteasome and is associated with neurodegenerative disorders (By similarity). Involved in DNA repair via homologous recombination (HR) by mediating deubiquitination of RAD51 in response to DNA damage, promoting interaction between RAD51 and BRCA2. Deubiquitinates ENAC in apical compartments, thereby regulating apical membrane recycling (By similarity). Indirectly increases the phosphorylation of IGFIR, AKT and FOXO1 and promotes insulin-signaling and insulin-induced adipogenesis (By similarity). Required for stress-response retinal, skeletal muscle and germ cell maintenance (By similarity). May be involved in working memory (By similarity).
Synonyms: UCH-L3
Tractability: Small molecule: a structure with a bound ligand is known; a high-quality ligand is known; it belongs to a druggable protein family. PROTAC: ubiquitination databases record sites on it; its protein half-life has been measured; a small molecule that binds it is known.
Target class: Cysteine protease CA clan; Cysteine protease; Enzyme; Protease; Cysteine protease C12 family
Gene: Protein-coding gene on chromosome 13 (75,549,483 to 75,607,472, forward strand). Ensembl gene ENSG00000118939.
Subcellular location: Cytoplasm
Subcellular location (Human Protein Atlas): Cytosol; Nucleoplasm; Golgi apparatus
Pathways (Reactome):
Metabolism of proteins: Neddylation; Synthesis of active ubiquitin: roles of E1 and E2 enzymes; UCH proteinases
Gene Ontology:
Molecular function: cysteine-type deNEDDylase activity; cysteine-type deubiquitinase activity; peptidase activity; protein binding; ubiquitin binding; deNEDDylase activity; deubiquitinase activity
Biological process: positive regulation of double-strand break repair via homologous recombination; protein deubiquitination; post-translational protein modification; protein catabolic process; protein ubiquitination; ubiquitin-dependent protein catabolic process
Cellular component: cytoplasm; cytosol
Genetic constraint (gnomAD): Loss-of-function variants: 15 observed, 24.5 expected, observed/expected ratio (o/e) 0.61, 90% interval 0.41 to 0.94. The upper end of that interval is the gene's LOEUF score, 0.94, which puts it in group 4 of 6, group 1 being the genes least tolerant of losing a copy. Missense variants: 192 observed, 232.18 expected, observed/expected ratio (o/e) 0.83, 90% interval 0.73 to 0.93. Synonymous variants: 75 observed, 77.31 expected, observed/expected ratio (o/e) 0.97, 90% interval 0.8 to 1.18.
Homologues: Orthologues: dog UCHL3 (100% identical), mouse Uchl3 (98% identical), rabbit UCHL3 (98% identical), pig UCHL3 (98% identical), rat Uchl3 (98% identical), mouse Uchl4 (96% identical), macaque UCHL3 (92% identical), rat Uchl3 (91% identical), tropical clawed frog uchl3 (74% identical), zebrafish uchl3 (74% identical), Caenorhabditis elegans ubh-1 (35% identical), Caenorhabditis elegans ubh-3 (35% identical), and 1 more. Paralogues in human: UCHL1 (53% identical), UCHL5 (29% identical), BAP1 (26% identical).
Diseases named in the same sentence as UCHL3 in open-access papers:
UCHL3 is named in the same sentence as 49 diseases in open-access papers, as found by Europe PMC text mining. Sharing a sentence is not in itself a finding about the gene and the disease. The quoted sentences say what the papers report.
breast carcinoma (10 papers, 2018 to 2025). "For instance, UCHL3 deficiency sensitizes thyroid cancer cells to chemotherapy, while its overexpression induces treatment resistance in breast cancers." (PMID 41271634, 2025). "Previous studies have indicated a significant upregulation of UCHL3 expression in several cancers, such as hepatocellular carcinoma, breast cancer, and colorectal cancer, correlating with poor prognosis and suggesting its potential as a therapeutic target." (PMID 41271634, 2025). "More recently, the Akt inhibitor perifosine has been suggested to inhibit UCHL3 in breast cancer cell lines." (PMID 35053210, 2022). "This selectivity also was demonstrated in the lysate assays, where the ABP proved to be selective for UCHL3 over other DUBs in the MDA-MB-231 breast cancer cells." (PMID 35053210, 2022). "Overexpression of UCHL3 in breast cancer cells makes them resistant to radiation and chemotherapy, while depletion of UCHL3 reverses the phenomena indicating a role of UCHL3 in cancer therapy." (PMID 36237424, 2022). "It is found that UCHL3 weakens radiosensitivity in breast cancer cells by deubiquitinating and activating Rad51." (PMID 34575114, 2021). "UCHL3 depletion sensitizes breast cancer cells to radiation and chemotherapy, while overexpression of UCHL3 renders cells resistant to these therapies." (PMID 31113933, 2019). "Consistent with our data, UCHL3 overexpression in breast cancer has been correlated with poor survival rates." (PMID 29898404, 2018). "This same variant was shown to selectively form covalent adducts with UCHL3 in MDA-MB-231 breast cancer cells and no reactivity toward other DUBs expressed." (PMID 35053210, 2022). "Furthermore, overexpression of UCHL3 has also been observed in breast cancer and is well correlated with poor survival rates." (PMID 35053210, 2022). "Likewise, according to clinical cases, UCHL3 overexpression functions as a prognostic index for unfavorable outcome in breast cancer patients." (PMID 34575114, 2021). "Thus, UCHL3 strengthens the HR signaling pathway in DNA repair, rendering breast cancer cells resistant to PARPi." (PMID 34575114, 2021). "Here, UCHL3-mediated deubiquitination of RAD51 protein, important in homologous recombination, was found to recruit BRCA2 protein, the key regulator of breast cancer." (PMID 36237424, 2022). "In summary, the ATM/ZEB1/USP7/CHK1, miR-200c/LINC02582/USP7/CHK1, USP7/PHF8, UCHL3/RAD51, USP52/ASF1A, and UCHL1/HIF-1 signaling axis are potential targets to improve the radiosensitivity of breast cancer." (PMID 34575114, 2021). "In addition, we performed Kaplan–Meier analysis in other cancer types, breast cancer (BRCA), kidney cancer (KIRC) and liver cancer (LIHC), which showed that UCHL3 levels were upregulated in these cancers." (PMID 32546741, 2020). "In a subsequent study, the same group focused on designing UCHL3-selective UbV-ABPs and developed UbVQ40V/T66K/V70F-ABP, which showed outstanding UCHL3 inhibition in vitro and reactivity for UCHL3 in MDA-MB-231 breast cancer cells without cross-reactivity with other DUBs." (PMID 37626927, 2023).
pancreatic cancer (7 papers, 2020 to 2025). "In particular, rs7985480, in LD with rs2274048, located in the 3'UTR of UCHL3, was associated with pancreatic cancer risk with at least p < 0.05 in all datasets." (PMID 34527018, 2021). "Expression of ubiquitin carboxy-terminal hydrolase L3 (UCHL3) was significantly increased in pancreatic cancer tissues and cells, and knockdown of UCHL3 significantly inhibited cell viability and aerobic glycolysis." (PMID 40630951, 2025). "Highly expressed UCHL3 is critical for aerobic glycolysis in pancreatic cancer because it stabilizes tumor promoter LDHA (lactate dehydrogenase A) expression." (PMID 37740194, 2023). "Deubiquitination of FOXM1 by UCHL3 was also shown to promote pancreatic cancer progression and gemcitabine resistance." (PMID 33680951, 2020). "However, oncogenic activities have also been reported with UCHL3 being overexpressed in lung cancer, ovarian cancer, pancreatic cancer, and melanoma." (PMID 36969045, 2023). "In pancreatic cancer, over-expressed ubiquitin carboxyl-terminal hydrolase L3 (UCHL3) was reported to stabilize Forkhead box protein M1 (FOXM1), which activates the transcription of LDHA, and promotes aerobic glycolysis of pancreatic cancer through the UCHL3-FOXM1-LDHA axis." (PMID 35307036, 2022). "Additionally, the role of deubiquitinase enzymes like USP5, UCHL3 and USP21 have been demonstrated to stabilize FOXM1 in pancreatic cancer, and basal like breast cancer (BLBC) respectively." (PMID 33680951, 2020).
non-small cell lung carcinoma (6 papers, 2021 to 2024). A group of at least three distinct histological types of lung cancer, including non-small cell squamous cell carcinoma, adenocarcinoma, and large cell carcinoma. "For example, UCHL3 contributes to non-small cell lung cancer cell growth by stabilizing TRAF2 (TNF receptor-associated factor 2)." (PMID 37740194, 2023). "UCHL3 maintains aryl hydrocarbon receptor (AhR) protein stability and confers cancer stem-like properties to non-small cell lung cancer cells, functioning as a tumor promoter." (PMID 37740194, 2023). "UCHL3 maintains AhR protein stability and thereby confers cancer stem-like properties to non-small cell lung cancer cells, functioning as a tumor promoter." (PMID 37740194, 2023). "Other examples include findings that UCHL3 is responsible for deubiquitination of lymphoid-specific helicase (LSH), a chromatin modifier linked to migration, invasion, and tumor formation in non-small cell lung cancer (NSCLC)." (PMID 35053210, 2022). "Moreover, UCHL3 in non-small cell lung cancers promotes stem-like characteristics and potent tumorigenic capacity by deubiquitinating the aryl hydrocarbon receptor." (PMID 38474064, 2024).
gastric cancer (4 papers, 2024 to 2025). A primary or metastatic malignant neoplasm involving the stomach. "Ubiquitin C-terminal hydrolase-L3 (UCH-L3) reduces β-catenin protein expression by inhibiting its ubiquitination during autophagy activation, aiding stress resistance in gastric cancer stem-like cells under nutrient deprivation." (PMID 39487556, 2024). "UCHL3 promotes gastric cancer metastasis by increasing IGF2 expression." (PMID 39605891, 2024). "Ubiquitin carboxyl-terminal hydrolase L3 (UCHL3) is a deubiquitinating enzyme involved in various cancers, yet its role in gastric cancer (GC) requires further exploration." (PMID 41271634, 2025).
lung carcinoma (4 papers, 2020 to 2023). "Inhibition of UCHL3 reduced stem-like characteristics, as shown by their decreased ability to form spheroids, suggesting that UCHL3 promotes stem-like characteristics in lung cancer." (PMID 32546741, 2020). "To clarify the role of UCHL3 in lung cancer, we used Western blotting to detect the expression of UCHL3 in 20 pairs of NSCLC tissues and paracancerous normal tissues." (PMID 32546741, 2020). "In conclusion, UCHL3 is an AhR DUB that promotes lung cancer proliferation, tumor growth and tumor stem-like properties through stabilizing AhR by its deubiquitination." (PMID 32546741, 2020). "In this paper, we found a new mechanism of AhR regulation and functional mechanism by which UCHL3 promotes lung cancer progression and stemness." (PMID 32546741, 2020). "We observed that both AhR and UCHL3 protein levels were increased in lung cancer tissues compared with normal tissues, and a positive correlation between AhR and UCHL3 protein levels was observed." (PMID 32546741, 2020). "We carried out immunohistochemical analysis of tissue samples obtained from lung cancer patients to further confirm the expression level of UCHL3 in lung cancer." (PMID 32546741, 2020). "The UCHL3 protein was detected in both lung cancer tissues and paracancerous normal tissues, and its expression was significantly elevated in lung ADC and SCC." (PMID 32546741, 2020). "Stemness-related genes and other stemness markers were elevated in lung cancer cells overexpressing UCHL3." (PMID 32546741, 2020). "To reveal the physiological role of UCHL3 in lung cancer, we stably knocked down UCHL3 in H358 cells." (PMID 32546741, 2020). "By ALDEFLUOR analysis, after UCHL3 depletion, the ALDH activity in H358 cells was decreased, suggesting that UCHL3 promotes stem-like properties in lung cancer." (PMID 32546741, 2020). "Furthermore, in stable UCHL3-knockdown H358 cells, expression of the AhR protein was downregulated, indicating that UCHL3 plays a key role in regulating AhR expression in lung cancer." (PMID 32546741, 2020). "Collectively, these findings indicate that inhibition of UCHL3 may effectively eliminate lung cancer stem cell properties by promoting AhR destabilization." (PMID 32546741, 2020). "Finally, UCHL3 functions to promote tumor growth and lung cancer stem-like properties through AhR." (PMID 32546741, 2020). "Our research indicates that UCHL3 might serve as a therapeutic target in lung cancer." (PMID 32546741, 2020). "Ubiquitin C-terminal hydrolase L3 (UCHL3) stabilizes aryl hydrocarbon receptor (AhR) by its deubiquitylation and subsequently increases ABCG2 to promote stem-like properties in lung cancer." (PMID 36694209, 2023).
ovarian carcinoma (4 papers, 2023 to 2024). A malignant neoplasm originating from the surface ovarian epithelium. "The high expression of UCHL1 in cervical squamous cell carcinoma, UCHL3 in ovarian cancer, and UCHL5 in lung adenocarcinoma are also used as markers of poor prognosis." (PMID 39034372, 2024). "Previously, UCHL3 has been found to be robustly expressed in epithelial ovarian cancer and related to intra-abdominal metastases." (PMID 37740194, 2023).
prostate carcinoma (4 papers, 2020 to 2023). A carcinoma that arises from epithelial cells of the prostate gland. "On the other hand, there are other DUBs, such as USP9X and UCHL3, that reduce their expression in prostate cancers." (PMID 35884607, 2022). "Previously, ubiquitin C-terminal hydrolase-L1 (UCH-L1) and ubiquitin C-terminal hydrolase-L3 (UCH-L3) were reported to be involved in prostate cancer cell progression through the epithelial-to-mesenchymal transition (EMT) regulation." (PMID 34745437, 2021). "By contrast, UCHL3 is reduced in metastatic prostate cancer cell lines, and knockdown of UCHL3 promotes epithelial-to-mesenchymal transition (EMT), contributing to cancer cell invasion and metastasis." (PMID 33585209, 2020). "Moreover, ubiquitin C-terminal hydrolase L1 (UCH-L1) and ubiquitin C-terminal hydrolase L3 (UCH-L3) differentially govern the stem-like traits in prostate cancer cells through regulating the PI3K/AKT pathway." (PMID 36969009, 2023). "Similarly, knockdown of UCHL3 promoted EMT in normal prostate cell lines and led to increased cell migration and invasion, whereas UCHL3 overexpression in prostate cancer cell lines reversed such processes." (PMID 35884607, 2022).
cervical carcinoma (3 papers, 2011 to 2025). A carcinoma arising from either the exocervical squamous epithelium or the endocervical glandular epithelium. "In cervical cancer studies, it has been found that UCHL3 promotes the development and metastasis of cervical cancer by stabilizing NRF2 through deubiquitination." (PMID 40258841, 2025).
lung adenocarcinoma (3 papers, 2018 to 2024). A carcinoma that arises from the lung and is characterized by the presence of malignant glandular epithelial cells. "Additionally, UCHL3 was shown to indicate poor prognosis in patients with lung adenocarcinoma." (PMID 32546741, 2020).
colorectal cancer (2 papers, 2019 to 2021). A primary or metastatic malignant neoplasm that affects the colon or rectum. "Here, we show that cancer-associated fibroblast (CAF)-activated stromal signaling, interleukin-6/8-JAK2, induces BRD4 phosphorylation at tyrosine 97/98 in colorectal cancer, resulting in BRD4 stabilization due to interaction with the deubiquitinase UCHL3." (PMID 34290255, 2021).
glioma (2 papers, 2024 to 2025). A benign or malignant brain and spinal cord tumor that arises from glial cells (astrocytes, oligodendrocytes, ependymal cells). "It has been shown that UCHL3 induces radiation resistance and the acquisition of mesenchymal phenotypes by deubiquitinating p12 in glioma stem cells." (PMID 40004517, 2025). "A recent study has opened a new area for further research, viz., the discovery that p12 is a target of UCHL3, a ubiquitin C-terminal hydrolase in glioma stem cells." (PMID 40004517, 2025). "Temozolomide combined with radiotherapy is the main treatment for glioma after surgery, in this study, we experimentally demonstrated that TCID, an inhibitor of UCHL3, has a specific synergistic effect on treatment, and the combination of the two can inhibit the growth of tumour to a greater extent." (PMID 38829550, 2024).
Insulin resistance (2 papers, 2012 to 2025). Increased resistance towards insulin, that is, diminished effectiveness of insulin in reducing blood glucose levels. "Morever, Uchl3−/− mice displayed a reduction of adipose tissue mass and were protected against high-fat diet-induced obesity and insulin resistance." (PMID 22679485, 2012). "It has been proposed that the rs4885322 SNP may influence UCHL3 gene expression, disrupting cellular Ub levels, which in turn could impair insulin signaling, promoting insulin resistance and hyperglycemia." (PMID 40002753, 2025).
liver cancer (2 papers, 2020 to 2023). An epithelial or non-epithelial malignant neoplasm that arises from the liver. "UCHL3 promoted migration of the liver cancer cells of the current study by deubiquitinating Vimentin." (PMID 36969045, 2023).
anaplastic thyroid cancer (1 paper, 2024). "UCHL3 increases the stability of the YAP protein in a deubiquitinating activity-dependent manner, thereby promoting the progression and metastasis of anaplastic thyroid cancer." (PMID 38474064, 2024).
asthenozoospermia (1 paper, 2016). "UCHL3 can be used as an indicator of sperm quality, fertilization and early embryo development in patients with asthenozoospermia and oligoasthenozoospermia." (PMID 27780264, 2016). "Here we examined the level and activity of UCHL3 in spermatozoa from men with asthenozoospermia (A), oligoasthenozoospermia (OA) or normozoospermia (N)." (PMID 27780264, 2016).
axonal neuropathy (1 paper, 2018). Any nerve disorder affecting the axon of a nerve. "In contrast, UCHL3 is downregulated in spinocerebellar ataxia with axonal neuropathy (SCAN1), causing elevated levels of TDP1 ubiquitylation and faster turnover rate." (PMID 29898404, 2018).
bladder (1 paper, 2023). "Our data demonstrated the tumor-promoting function of UCHL3 in bladder cancer, suggesting that targeting UCHL3 might be a potential approach for preventing bladder tumorigenesis and progression." (PMID 37740194, 2023).